Y_RNA (Y RNA )
Gene: Miscellaneous RNA gene on chromosome X (136,571,705 to 136,571,815, reverse strand). Ensembl gene ENSG00000199424.
Homologues: Orthologues: chimpanzee Y_RNA (99% identical), guinea pig Y_RNA (87% identical), macaque Y_RNA (86% identical), guinea pig Y_RNA (83% identical). Paralogues in human: RNY1 (82% identical), RNY1P5 (82% identical), Y_RNA (80% identical), Y_RNA (79% identical), RNY1P4 (78% identical), Y_RNA (78% identical), Y_RNA (77% identical), Y_RNA (76% identical), RNY1P11 (75% identical), RNY1P8 (75% identical), Y_RNA (75% identical), RNY1P2 (74% identical), and 90 more.